INF2 (inverted formin 2)
Description:
Severs actin filaments and accelerates their polymerization and depolymerization.
Synonyms: C14orf151; C14orf173; MGC13251; CMTDIE; FSGS5; pp9484
Tractability: Small molecule: a structure with a bound ligand is known. PROTAC: ubiquitination databases record sites on it; its protein half-life has been measured.
Gene: Protein-coding gene on chromosome 14 (104,681,146 to 104,722,535, forward strand). Ensembl gene ENSG00000203485.
Subcellular location: Cytoplasm, perinuclear region
Subcellular location (Human Protein Atlas): Endoplasmic reticulum; Nuclear bodies
Gene Ontology:
Molecular function: protein binding; actin binding; small GTPase binding
Biological process: regulation of mitochondrial fission; actin filament polymerization; actin cytoskeleton organization
Cellular component: perinuclear region of cytoplasm; actin filament
Genetic constraint (gnomAD): Loss-of-function variants: 42 observed, 103.26 expected, observed/expected ratio (o/e) 0.41, 90% interval 0.32 to 0.53. The upper end of that interval is the gene's LOEUF score, 0.53, which puts it in group 2 of 6, group 1 being the genes least tolerant of losing a copy. Missense variants: 1,277 observed, 1,458.9 expected, observed/expected ratio (o/e) 0.88, 90% interval 0.83 to 0.92. Synonymous variants: 746 observed, 653.99 expected, observed/expected ratio (o/e) 1.14, 90% interval 1.07 to 1.21.
Gene-disease validity (ClinGen):
ClinGen rates the evidence that INF2 causes each of these diseases.
Charcot-Marie-Tooth disease dominant intermediate E (autosomal dominant): Definitive.
Homologues: Orthologues: chimpanzee INF2 (99% identical), macaque INF2 (94% identical), mouse Inf2 (80% identical), rat Inf2 (79% identical), guinea pig INF2 (76% identical), tropical clawed frog inf2 (54% identical), Caenorhabditis elegans daam-1 (15% identical), Caenorhabditis elegans exc-6 (14% identical), Caenorhabditis elegans sydn-1 (5% identical). Paralogues in human: DIAPH1 (20% identical), FMN2 (20% identical), DAAM2 (18% identical), DIAPH3 (18% identical), DAAM1 (18% identical), DIAPH2 (18% identical), FMNL1 (17% identical), FMNL3 (16% identical), FMNL2 (16% identical), FHDC1 (16% identical), FHOD3 (15% identical), GRID2IP (15% identical), and 6 more.
Diseases named in the same sentence as INF2 in open-access papers:
INF2 is named in the same sentence as 81 diseases in open-access papers, as found by Europe PMC text mining. Sharing a sentence is not in itself a finding about the gene and the disease. The quoted sentences say what the papers report.
focal segmental glomerulosclerosis (21 papers, 2014 to 2026). A renal disorder characterized by sclerotic lesions in the glomeruli. "In 2011, it was discovered that INF2 variants caused focal segmental glomerulosclerosis (FSGS) and CMT." (PMID 40985697, 2026). "INF2 belongs to the formin family of actin nucleators and has been associated with various diseases such as focal segmental glomerulosclerosis (FSGS) and the neurological disorder Charcot-Marie-Tooth (CMT) disease." (PMID 39317734, 2024). "Mutations in the INF2 DID are linked to focal segmental glomerulosclerosis (FSGS), affecting podocytes, and Charcot-Marie-Tooth disease, which affects Schwann cells and leads to axonal loss." (PMID 39586895, 2024). "In the last 10 years, the inverted formin 2 (INF2) has been an important target of mutations responsible for focal segmental glomerulosclerosis (FSGS)." (PMID 33541266, 2021). "One proband had waited till his sixth decade for a genomic diagnosis of an INF2 mutation causing focal segmental glomerulosclerosis." (PMID 34758253, 2021). "Formin mutations can result in various forms of pathologies like the Charcot-Marie-Tooth-Syndrome and Focal Segmental Glomerulosclerosis (FSGS) which are associated with mutations of INF2." (PMID 34043722, 2021). "Mutations in the inverted formin-2 (INF2) gene were identified in patients with Charcot-Marie-Tooth (CMT) disease combined with focal segmental glomerulosclerosis (FSGS)." (PMID 32033020, 2020). "As with DGKE, genetic pleiotropism is also seen with most individuals with INF2 mutations presenting with focal segmental glomerulosclerosis (FSGS) and nephrotic syndrome." (PMID 29327071, 2018). "Mutations in INF2 are linked to two human genetic diseases: focal and segmental glomerulosclerosis (FSGS), a degenerative kidney disease, and Charcot-Marie-Tooth disease (CMTD), a neurological disorder." (PMID 28448495, 2017). "Mutations in inverted formin 2 (INF2) cause focal segmental glomerulosclerosis (FSGS) a major cause of end-stage kidney disease." (PMID 26764407, 2016). "Individuals who have INF2 mutations may experience focal segmental glomerulosclerosis, a condition that can quickly lead to end-stage renal disease." (PMID 39328666, 2024). "INF2 mutations cause focal segmental glomerulosclerosis (FSGS) and Charcot–Marie–Tooth disease (CMT)." (PMID 40985697, 2026). "Mutations in the human INF2 gene cause autosomal dominant focal segmental glomerulosclerosis (FSGS)—a condition characterized by podocyte loss, scarring, and subsequent kidney degeneration." (PMID 38916773, 2024). "Missense variants in the INF2-DID domain were first identified as the cause of familial focal segmental glomerulosclerosis (FSGS), an inherited kidney disorder characterized by progressive scarring of the glomeruli." (PMID 39337270, 2024). "Heterozygous mutations in the inverted formin 2 (INF2) gene are related to secondary focal segmental glomerulosclerosis (FSGS), a rare secondary disease associated with rapidly progressive renal failure." (PMID 33541266, 2021). "Mutations in INF2 are frequently responsible for focal segmental glomerulosclerosis (FSGS), which is a common cause of end stage renal disease (ESRD); additionally, they are also connected with Charcot-Marie-Tooth neuropathy." (PMID 30126379, 2018). "Mutations in INF2, an actin assembly factor, cause two diseases: peripheral neuropathy CMT-DIE (MIM614455) and/or focal segmental glomerulosclerosis (FSGS)." (PMID 39857711, 2025). "Pathogenic variants of inverted formin 2 (INF2) CAAX isoform, an actin assembly factor that is predominantly expressed in the endoplasmic reticulum (ER), are linked to focal segmental glomerulosclerosis (FSGS) and Charcot–Marie–Tooth (CMT) neuropathy." (PMID 39337270, 2024). "Mutations in Inverted Formin 2 (INF2), a diaphanous formin family protein that regulates actin cytoskeleton dynamics, cause focal segmental glomerulosclerosis (FSGS) and Charcot–Marie–Tooth Disease (CMT) in humans." (PMID 26086034, 2014).
glomerulopathy (8 papers, 2014 to 2025). "Diseases like HIVAN and familial forms of glomerular disease such as mutations in α-actinin-4 and inverted formin-2 (INF-2) probably affect the podocyte actin cortical cytoskeleton." (PMID 27942003, 2016). "How mutations in INF2, causing Charcot–Marie–Tooth disease type 2D and glomerulopathy affect this process remains to be determined." (PMID 26744348, 2016). "Mutations in the DID domain of the formin family member, INF2, have recently been associated with FSGS and in Charcot–Marie–Tooth disease with glomerulopathy." (PMID 26764407, 2016). "Another example of an ER-bound protein that modulates mitochondrial dynamics is INF2, mutations in which cause CMT associated with glomerulopathy." (PMID 26744348, 2016). "The simple zebrafish model that we employ here should be useful for both the further dissection of the biological pathways involved in INF2 mediated human glomerular disease, and perhaps INF2 mediated neurological disease as well." (PMID 26086034, 2014). "Mutations in the genes that code for proteins that are expressed in podocytes including nephrin, podocin, WT1, α-actinin-4, inverted formin 2 (INF2), TrpC6, MYH9, and phospholipase Cε1, lead to glomerular disease." (PMID 27942003, 2016).
nephrotic syndrome (6 papers, 2015 to 2022). A collection of symptoms that include severe edema, proteinuria, and hypoalbuminemia; it is indicative of renal dysfunction. "Mutations in inverted formin 2 (INF2), a member of the formin family of actin-regulating proteins, have recently been associated with a familial cause of nephrotic syndrome characterized by FSGS." (PMID 26764407, 2016). "Mutations in proteins influencing the actin dynamics (e.g., α-actinin-4, INF2, CDC42) are known to cause kidney injuries including nephrotic syndrome or FSGS31–34." (PMID 30154411, 2018).
neuropathy (5 papers, 2023 to 2026). A disorder affecting the nervous system that manifests with pain, tingling, numbness, and/or muscle weakness. "Further studies with hypertrophic features will help discover the molecular mechanisms underlying schwannoma tumorigenesis and neuropathies and improve therapeutic strategies in INF2 disorders." (PMID 39857711, 2025). "Accurate genetic diagnosis is critical, as INF2‐related FSGS is typically resistant to immunotherapy yet rarely recurs after transplantation, and its associated neuropathy can mimic treatable immune‐mediated disorders such as chronic inflammatory demyelinating polyradiculoneuropathy (CIDP)." (PMID 40985697, 2026). "Furthermore, INF2‐related neuropathy mimics immune‐mediated disorders, such as chronic inflammatory demyelinating polyradiculoneuropathy (CIDP), potentially leading to inappropriate immunotherapy." (PMID 40985697, 2026).
prostate carcinoma (4 papers, 2017 to 2025). A carcinoma that arises from epithelial cells of the prostate gland. "A dominant negative effect probably causes SPOP mutant forms associated with prostate cancer to be defective in promoting INF2 ubiquitination, resulting in increased localization of INF2 at the endoplasmic reticulum." (PMID 34685534, 2021). "Speckle-type POZ protein (SPOP), which is one of the most frequently mutated genes in prostate cancer, is an adapter that brings INF2 and other substrates to the proximity of specific E3 ubiquitin ligase complexes for ubiquitination." (PMID 34685534, 2021). "Next, we investigated the impact of prostate cancer-associated mutants of SPOP on INF2 localization." (PMID 28448495, 2017). "Moreover, in vivo ubiquitination assay indicated that prostate cancer-associated SPOP mutants largely lost the capacity to promote INF2 polyubiquitination." (PMID 28448495, 2017). "We postulated that prostate cancer-associated mutants of SPOP may be defective in mediating INF2 polyubiquitination." (PMID 28448495, 2017). "Moreover, prostate cancer-associated SPOP mutants increase INF2 localization in ER and promote mitochondrial fission, probably through a dominant-negative effect to inhibit endogenous SPOP." (PMID 28448495, 2017). "Taken together, our findings suggest that INF2 ubiquitination may be dysregulated by oncogenic prostate cancer-associated SPOP mutants." (PMID 28448495, 2017). "SPOP inactivation-induced prostate cancer cell migration and invasion is partly mediated by INF2 and mitochondrial fission." (PMID 28448495, 2017). "Maybe most interestingly in regard to our data on promotion of prostate cancer cell motility by PIM1 and NFATC1, there were several genes encoding regulators of the cytoskeletal actin network (INF2, FHOD1, ACTN3, CORO1B) and cell adhesion (COL6A2, PXN, ITGA5)." (PMID 31730483, 2019). "We hypothesized that prostate cancer-associated mutations of SPOP might disrupt the interaction between wild-type SPOP and INF2." (PMID 28448495, 2017). "Next, we decided to extend our analysis by investigating whether endogenous SPOP and INF2 can interact with each other in prostate cancer cells." (PMID 28448495, 2017). "Considering INF2 is an important regulator of actin polymerization and mitochondrial fission, we explored whether INF2 is an authentic SPOP substrate and its function is dysregulated in SPOP-mutated prostate cancer." (PMID 28448495, 2017). "Moreover, INF2 is important for SPOP inactivation-induced prostate cancer cell migration and invasion." (PMID 28448495, 2017). "Taken together, our data suggest that wild-type SPOP, but not prostate cancer-associated mutants, can suppress INF2-mediated mitochondrial fission." (PMID 28448495, 2017). "Taken together, our data suggests that wild-type SPOP, but not prostate cancer-associated mutants, can promote INF2 disassociation from ER." (PMID 28448495, 2017). "Among these genes, high expression of certain genes, such as FLNA and DSTN, is positively correlated with the prognosis of prostate cancer patients, while elevated expression of other genes, including FLNB and INF2, is associated with a negative prognosis." (PMID 41049007, 2025). "Moreover, we found that ectopic expression of SPOP in LNCaP or DU145 prostate cancer cells did not alter the protein level of endogenous INF2." (PMID 28448495, 2017). "In contrast, two prostate cancer-associated SPOP mutants lacking the NLS sequence (SPOP-F125V-ΔNLS, SPOP-F133L-ΔNLS) accumulated exclusively in the cytoplasm as puncta pattern similar as SPOP-ΔNLS, but these mutants did not co-localize with GFP-INF2, possibly due to impaired interaction with INF2." (PMID 28448495, 2017).
renal failure (4 papers, 2016 to 2026). "The main phenotypic clue in patients with causative INF2 variants was the history of kidney disease in various degrees ranging from asymptomatic proteinuria to renal failure requiring transplantation." (PMID 39776111, 2025). "Here, we report a new familial autosomal INF2 mutation in exon 4 (p.Arg214Cys) present in two patients from the same three-generation family of Chinese origin; these patients presented with proteinuria, high blood pressure, and hyperuricemia, and exhibited rapid progression of renal failure." (PMID 33541266, 2021). "Renal histopathology in INF2‐associated FSGS typically shows glomerular tuft collapse with focal segmental sclerosis and thinning of the glomerular basement membrane; clinically, these changes correlate with the development of proteinuria and eventual renal failure." (PMID 40985697, 2026).
breast carcinoma (3 papers, 2018 to 2023). "Grade I-II breast cancers had more INF2, INF3, INF4, INF5 and INF9 cells, while those of grade > II were enriched for INF0, INF1 and INF6 cells, which indicated more locally aggregated inflammatory cells." (PMID 37880211, 2023). "Studies suppressing dynamin-related protein 1 (Drp1)—a fission protein whose recruitment to mitochondria is facilitated by INF2 —in breast cancer cells inhibited formation of lamellipodia and suppressed their migration and invasion capabilities." (PMID 29309034, 2018).
Charcot-Marie-Tooth disease (3 papers, 2016 to 2024). An inherited degenerative disorder involving the peripheral nerves. "INF2-gene mutations were identified in both FSGS and Charcot-Marie-Tooth disease, a hereditary motor and sensory neuropathy that is characterized by peripheral nerval demyelination." (PMID 27733133, 2016). "Renal transplantation, however, can be considered a curative treatment for patients without neurological manifestation (Charcot-Marie-Tooth disease), provided the donor kidney expresses functional INF2." (PMID 27733133, 2016).
Charcot-Marie-Tooth neuropathy (3 papers, 2018 to 2025). "Mutations in INF2 are not only connected with FSGS, but also with Charcot-Marie-Tooth neuropathy." (PMID 30126379, 2018). "Interestingly, the INF2 inhibitory KAc-actin/CAP complex has been initially purified from mouse brain, and disease-linked INF2 mutations (including mutations linked to Charcot-Marie-Tooth neuropathy) were only poorly inhibited by this complex, suggesting a disease contribution of this interaction." (PMID 39154297, 2024).
end-stage renal disease (3 papers, 2018 to 2024). "The onset of end-stage renal disease in patients with the INF2 L76P mutation, which causes solely FSGS, occurs over a range of ages of 28–70 years." (PMID 38916773, 2024).
endometrial cancer (3 papers, 2023 to 2024). Primary or metastatic malignant neoplasm involving the endometrium (mucous membrane that lines the endometrial cavity). "In this study, we demonstrate that INF2 expression is significantly upregulated in endometrial cancer (EC) and is associated with a poor prognosis in EC patients." (PMID 38233384, 2024). "Taken together, these results indicate that INF2 plays a pivotal role in promoting the malignant proliferative potential of endometrial cancer, as also verified in another EC cell line, Ishikawa cells." (PMID 38233384, 2024). "INF2 protein in the ER can trigger mitochondrial division by recruiting DRP1 protein, and elevated INF2 has been significantly, negatively correlated with the hypocancerous FBXO7 protein in endometrial cancer specimens." (PMID 38711526, 2024). "Under energetic stress conditions, AMPK induces phosphorylation of INF2 (Ser1077), leading to its increased localization to the ER, which enhances DRP recruitment to mitochondria and promotes endometrial cancer cell growth." (PMID 38711526, 2024). "Furthermore, by using endogenous antibodies to precipitate INF2 protein from HEC-1B and Ishikawa endometrial cancer cells, we confirmed the presence of endogenous AMPKα1/α2 protein." (PMID 38233384, 2024).